IGF1R (insulin like growth factor 1 receptor)
Diseases named in the same sentence as IGF1R in open-access papers (continued):
Sharing a sentence is not in itself a finding about the gene and the disease.
hepatocellular carcinoma (continued). "In hepatoma cells (SMMC-7721, BEL-7404, or Huh-7) IGF-1R also served as the common target when miR-223 inhibited the cell growth." (PMID 22073238, 2011). "For instance, in hepatocellular carcinoma, IGFBP1 acts as an inhibitor of IGF-1R pathway signaling." (PMID 41488652, 2025). "Given that miR-379 could suppress the IGF1/IGF1R and PI3K/AKT signaling pathway in hepatocellular carcinoma, and DLK1 is the potential target gene of miR-329 that may be involved in IGF1 signaling and muscle growth through Akt phosphorylation." (PMID 34527673, 2021). "Type 1 receptor (IGF1R) is reported to interact with insulin-like growth factor 1 and 2 (IGF1 and IGF2) for increasing fibrosis and impair liver functions from the start of preneoplastic alterations up to the developed hepatocellular carcinoma (HCC) stage." (PMID 34336665, 2021). "We suggest that loss of GSTZ1‐1 results in the accumulation of the oncometabolite SA, alkylation of KEAP1, and NRF2 activation, promoting IGF1R transcription by recruiting SP1 to its promoter, which promotes the antiapoptotic pathway of hepatoma cells in vitro and in vivo." (PMID 31267557, 2019). "For example, miRNA-122 inhibits the tumorigenic properties of hepatocellular carcinoma cells by repressing ADAM10 (a disintegrin and metalloprotease family 10), SRF (serum response factor), and Igf1R (insulin-like growth factor 1 receptor), which promote tumorigenesis." (PMID 28159933, 2017). "For instance, endogenous miR-142 and miR-223 from human macrophages were shown to be transferred to hepatocellular carcinoma cells (HCC), which resulted in decreased expression of stathmin-1 and insulin-like growth factor-1 receptor and inhibition of proliferation." (PMID 26861303, 2016). "In hepatocellular carcinoma (HCC), the glycosyltransferase GALNT14 mediates O-glycosylation of PHB2, enhancing tumor cell proliferation, migration, and chemotherapy resistance through activation of the insulin-like growth factor 1 receptor (IGF1R) signaling cascade." (PMID 40868286, 2025). "In hepatocellular carcinoma (HCC), BACH1 upregulates the expression of cell motility-related genes, such as insulin-like growth factor 1 receptor (IGF1R) and protein tyrosine kinase 2 (PTK2), to facilitate the growth and metastasis of HCC." (PMID 38321558, 2024). "Therefore, both IGF1-R inhibitors could enhance the pro-apoptotic and antiproliferative impacts of regorafenib and VK1 in hepatocellular carcinoma downregulating both MAPK and PI3K/AKT signaling pathways." (PMID 33768092, 2021). "Similarly, hepatoma cells are able to overcome IGF1R inhibition through HER3 activation in an EGFR-dependent mechanism, suggesting HER3 is an important mediator in acquired resistance to anti-IGF1R therapy." (PMID 25400118, 2014). "Several components of the IGF signaling axis, such as IGF-1, IGF-2 and IGF-1R, are deregulated during HCV-related human hepatocellular carcinoma (HCC)." (PMID 25333772, 2014). "With its secreted ligands, IGF1 and IGF2, Insulin-like growth factor 1 receptor (IGF1R) is highly expressed in many human cancer cells, including gastric (GC) and hepatocellular carcinoma (HCC)." (PMID 22438913, 2012). "Moreover, a correlation analysis of 363 patients with HCC included in the TCGA Liver Hepatocellular Carcinoma (LIHC) dataset showed a negative correlation between mRNA expression of GSTZ1‐1 and IGF1R (r = −0.31, P < 0.0001, n = 363)." (PMID 31267557, 2019).
Ewing sarcoma (132 papers, 2008 to 2025). A small round cell tumor that lacks morphologic, immunohistochemical, and electron microscopic evidence of neuroectodermal differentiation. "Compensatory activation of the insulin receptor (IR) and its mitogenic ligand IGF2 is triggered in some Ewing sarcoma cells in response to IGF2BP3 mediated IGF1R loss." (PMID 40442778, 2025). "Studies in Ewing Sarcoma cell lines have also shown that inhibition of N-linked glycosylation of IGF-1R downregulated the plasma membrane bound IGF-1R and consequently decreased the IGF-1R signaling and EWS cell survival." (PMID 37474760, 2023). "The positive association of the IGF-1R gene and protein level with tumor grade, metastasis, and recurrence was detected in the osteosarcoma and Ewing sarcoma groups." (PMID 36713521, 2022). "It was shown that inhibition of EWS::FLI1protein was associated with reduced IGF-1/IGF-1R signaling and induced Ewing sarcoma apoptosis and death that is postulated to be related to the interaction of IGF-1R and focal adhesion kinase (FAK)." (PMID 36713521, 2022). "In Ewing sarcoma, this oncofetal protein can mediate IGF1R loss and subsequent compensatory IRA and IGF2 activation in some cell lines." (PMID 33260481, 2020). "Biochemical and histological/immunohistochemical ex vivo analyses confirmed a reduced activation of ERBB4, EGFR, INSR, IGF1R, associated with apoptosis induction and angiogenesis inhibition in a drug-treated Ewing's sarcoma family tumor xenograft." (PMID 27374103, 2016). "We report here significant efficacy of CDK4/6 and IGF-1R inhibitors on a rare Ewing's sarcoma with FUS-ERG fusion and CDKN2A/B loss in a PDOX model." (PMID 27286459, 2016). "The administration of figitumumab, an anti-IGF-1R mAb, has been associated with objective responses in Ewing sarcoma patients, whereas R1507, another IGF-1R antagonist mAb, had mixed results in two studies." (PMID 26587548, 2015). "IGF-1R has been implicated in the development of sarcomas and inhibition of IGF-1R function has been demonstrated to reduce growth in OS, rhabdomyosarcoma, and Ewing sarcoma cell lines." (PMID 23755370, 2013). "Similarly, preclinical data on Ewing sarcoma indicate the ability of combinatorial approaches with anti-IGF1R to promote antitumor activity when associated with mTOR inhibitors or chemotherapy (trabectedin)." (PMID 40909947, 2025). "Because Ewing sarcoma has been shown to have susceptibility to IGF1R inhibitors, with modest activity observed in clinical trials, this novel combination may prove interesting in Ewing sarcoma and will be the focus of future investigation." (PMID 26337082, 2015). "However, the role of germline PTPRD mutations in predisposition to Ewing sarcoma, a disease of children, adolescents, and young adults, and the implications of these mutations for therapy with IGF-1R and STAT3 inhibitors warrants further investigation." (PMID 23800680, 2013). "It has also been shown that EWS-FLI1, the genetic hallmark of Ewing sarcoma, is only capable of transformation in the presence of IGF-1R and, more recently, that this fusion product directly affects IGF-1R signalling either by downregulating IGFBP3, increasing IGF1 promoter, or both." (PMID 21647361, 2011). "Finally, we propose that autocrine loops and other secondary mutations could be the reason for the failure of IGF1R inhibitors in Ewing sarcoma and other solid tumors." (PMID 33260481, 2020). "In Ewing sarcoma, IGF2BP3 loss promotes the downregulation of IGF1R and a decreased biological response to IGF1." (PMID 40442778, 2025). "Geldanamycin destabilised TRKAI isoform localisation on NB cell surface and reduced TRKAIII splice variant phosphorylation, reduced protein levels of IGF1R and KIT in Ewing sarcoma cells, and improved IGF1R inhibitor activity in murine xenografts." (PMID 41511287, 2025).
Ewing sarcoma (continued). "Early-phase clinical trials of IGF-1R-targeted antibodies in Ewing sarcoma reported a partial response in 10–14% of patients, but responses were short-lived." (PMID 40983796, 2025). "Previous analysis of autocrine signaling circuits in Ewing sarcoma identified the activity of IGF1 (IGF2)/IGF1R signaling in both Ewing sarcoma cells and patient tissues." (PMID 38906855, 2024). "Given prior reports documenting upregulation of the IGF/IGF-1R axis with Ras/Rac1 signaling in Ewing sarcoma, we performed immunohistochemistry on tumors from the micro-metastatic in vivo experiment." (PMID 38534214, 2024). "Expression of IGF1R is highest for the rhabdomyosarcoma and Wilms tumor models, and lower and more variable for osteosarcoma, neuroblastoma, and Ewing sarcoma models." (PMID 39510293, 2024). "This approach of separating shear stress and mass transport influences was applied to investigate the effect of shear stress on Ewing sarcoma cell sensitivity to Insulin growth factor-receptor (IGF-1R) inhibitors." (PMID 37830183, 2024). "The insulin-like growth factor 1 receptor (IGF1R) plays a significant role in Ewing sarcoma, contributing to tumor growth, survival, and metastasis." (PMID 37894854, 2023). "One study associated exclusively nuclear IGF-1R with better progression-free and overall survival in patients with soft tissue sarcomas, Ewing sarcomas and osteosarcomas treated with IGF-1R-directed antibodies." (PMID 37858153, 2023). "EHD1 is overexpressed in Ewing sarcoma and required for metastasis and tumorigenesis while regulating cellular trafficking and plasma membrane expression of IGF-1R." (PMID 37474760, 2023). "Though NT-157 has yet to be approved for use clinically, several IGF-1R inhibitors, including cixutumumab, have proved to be well-tolerated and effective in stabilizing several advanced cancers including Ewing’s sarcoma and adrenocortical carcinoma." (PMID 38036546, 2023). "The mechanism of action of IGF1R in Ewing sarcoma involves the activation of signaling pathways that promote cell proliferation, inhibit apoptosis (programmed cell death), and enhance tumor cell motility." (PMID 37894854, 2023). "In Ewing sarcoma cells with constitutive nuclear IGF-1R, treatment with the kinase inhibitor Linsitinib reduced the level of ubiquitinated-PCNA, thus likely attenuating DDT." (PMID 37858153, 2023). "Investigating the relevance of IGF-1R over-expression with poor outcomes and survival of Ewing sarcoma remained inconclusive and it seemed that contradictions need to be verified by future mechanistic surveys." (PMID 36713521, 2022). "For example, anti-IGF-1R monoclonal antibody therapy can only be effective in a few patients with specific tumor types such as Ewing sarcoma and thymoma." (PMID 35680570, 2022). "IGF1R is highly expressed and biologically active in small cell lung cancer, pediatric high-grade gliomas, and Ewing’s Sarcoma." (PMID 35399006, 2022). "A significantly elevated level of IGF-1R gene and protein was detected in bone tumors compared to the noncancerous bone tissues that were prominent in osteosarcoma and Ewing sarcoma compared to the GCT group." (PMID 36713521, 2022). "Studies have shown that the inhibitors of tyrosine kinase and anti-IGF-1R antibodies have good therapeutic potential in Ewing sarcoma." (PMID 35680570, 2022). "IGF-1 and IGF-1R are overexpressed in the majority of Ewing sarcoma cell lines and have been previously studied as potential therapeutic targets in tumor treatment." (PMID 35454895, 2022). "For this reason, finding the optimal IGF-1R inhibitors can provide new ideas and options for the treatment of Ewing sarcoma." (PMID 35680570, 2022). "To verify that the effects of the ZINC000014946303 and ZINC000006003042 were due to their inhibition of IGF-1R in Ewing sarcoma cells, we assessed levels of IGF-1R using Western blotting." (PMID 35680570, 2022).
Ewing sarcoma (continued). "Examining the IGF-1 family revealed an increase in the gene and protein level of IGF-1R in bone tumors of osteosarcoma and Ewing sarcoma compared to tumor margins as well as the circulating level of IGF-1, IGFBP-, and IGFBP-3 in these patients." (PMID 36713521, 2022). "Hereby, finding the optimal IGF-1R inhibitors can provide new ideas and options for treating Ewing sarcoma." (PMID 35680570, 2022). "The tumor tissues of osteosarcoma (0.2391) and Ewing sarcoma (0.1565) groups expressed higher level of IGF-1R compared to the tumor margins (0.029) (P < 0.0001); while the difference between GCT (0.03356) and margins was not notable." (PMID 36713521, 2022). "These dependencies are consistent with previous reports of dependencies on IGF1R in Ewing’s sarcoma and rhabdomyosarcoma." (PMID 35382456, 2022). "In Ewing sarcoma, IGF-1R binds to IGF to initiate SRC, MAPK, FAK, and other signaling pathways to synergistically stimulate the proliferation, survival, and migration of cancer cells in Ewing sarcoma." (PMID 35680570, 2022). "Another prominent cancer-type-specific association found by SuperDendrix is increased dependency on IGF2BP1, a regulator of insulin growth factor receptor IGF1R, in Ewing’s sarcoma and neuroblastoma." (PMID 35382456, 2022). "The clinical activity of anti-IGF-1R mAb has been demonstrated to have a sustained response in a few patients with specific tumor types such as Ewing sarcoma and thymoma." (PMID 35680570, 2022). "This study aims to screen out novel and promising IGF-1R targeting agents which can treat Ewing sarcoma." (PMID 35680570, 2022). "As a result, Ewing sarcoma cells are characterized by a unique autocrine loop, mediated by the IGF1R/IGF1 axis, which strongly contributes to cellular malignancy." (PMID 34440844, 2021). "Enhanced expression of the IR-A and its mitogenic ligand IGF2 is a major mechanism of resistance to anti-IGF1R therapy in Ewing sarcoma." (PMID 34440844, 2021). "BET inhibitors inhibited autocrine IGF1 action and activation of the IGF1R/Akt pathway in Ewing sarcoma cells." (PMID 34440844, 2021). "Accordingly, combination of trabectedin with anti-IGF1R mAb AVE1642 promoted antitumor activity in Ewing sarcoma xenografts." (PMID 34440844, 2021). "Pharmacological blockade of the IGF1R using mAbs or TKIs inhibited Ewing sarcoma cells proliferation, soft-agar growth, migration and inhibited downstream signalling, increased apoptosis, and blunted in vivo tumor growth." (PMID 34440844, 2021). "Nonetheless, a few patients with Ewing sarcoma experienced a long-term response to IGF1R inhibitor therapy." (PMID 33260481, 2020). "High IGF1-R expression was observed in Ewing sarcoma, and this tumor is regarded as a candidate for targeted therapy." (PMID 31963219, 2020). "In support of this, it has been shown that IGF1R inhibition can lead to compensatory IR activation in colorectal cancer, ovarian carcinoma, and Ewing sarcoma in vitro." (PMID 33260481, 2020). "Efficacy of Insulin-like growth factor 1 receptor (IGF-1R) inhibitors in combination with other inhibitors in treating Ewing sarcoma." (PMID 32754598, 2020). "Preclinical results encouraged the enrollment of STS patients in early-phase clinical trials of IGF1-R inhibitors, one of which is figitumumab, whose clinical efficacy against STSs including Ewing sarcoma was evaluated." (PMID 31963219, 2020). "Firstly, single-agent activity has been observed in trials of patients with Ewing sarcoma, clinical evaluation of IGF-1R mAB Ganitumab is ongoing in patients with Ewing and rhabdomyosarcoma, and Ganitumab has been granted orphan drug status in Ewing sarcoma." (PMID 31416218, 2019). "Firstly, most antibodies do show response in in vivo models, and secondly, clinical response to single-agent anti-IGF-1R is reported in some patients, particularly in Ewing’s sarcoma." (PMID 31600876, 2019).
Ewing sarcoma (continued). "Several clinical trials have been conducted to evaluate the efficacy of IGF-1R inhibition in Ewing sarcoma patients." (PMID 31676869, 2019). "Since IGF-1R signalling is also activated in small round cell sarcomas including Ewing sarcomas and rhabdomyosarcomas, these findings raise the possible relationship between the tumor morphology and activated signalling pathway in sarcomas." (PMID 31676869, 2019). "For example, figitumumab is one of the IGF1R inhibitors subjected to clinical trials of its efficacy and safety for patients with Ewing sarcomas." (PMID 30487384, 2018). "In a phase 2 clinical trial, ganitumab, another IGF1R-targeted drug, also produced objective responses to Ewing sarcoma and other tumors in the Ewing sarcoma family." (PMID 30487384, 2018). "Blockage of IGF-1R by a monoclonal antibody inhibits the xenograft tumorigenicity of Ewing sarcoma cells." (PMID 29321818, 2017). "Despite early accomplishments in pre-clinical investigations, in clinical trials, relatively few tumor types, e.g., Ewing sarcoma and thymoma, exhibited sustained responses to IGF-1R inhibitors." (PMID 28046018, 2017). "Activation of the IGF1R pathway in Ewing sarcoma is critically sustained by IGF1 produced by tumor cells." (PMID 27259270, 2016). "In future studies, dual inhibitors of both the IGF1R and the IR are preferably chosen because it has been shown in osteoblasts and Ewing sarcoma cells that cells can circumvent inhibition of IGF1R by increasing IR signalling." (PMID 27418340, 2016). "Repression of autocrine IGF1 by BET inhibitors led to significant inhibition of the IGF1R/AKT pathway critical to Ewing sarcoma cell proliferation and survival." (PMID 27259270, 2016). "The resultant IGF1 autocrine loop is essential to sustain adequate activation of the IGF1R/PI3K/AKT signaling pathway in Ewing sarcoma." (PMID 27259270, 2016). "IGF-1R antibodies demonstrated clinical activity in phase 2 studies in small number of patients with select tumor types including Ewing sarcoma, thymoma and thymic carcinoma." (PMID 27127884, 2016). "Recent evidence suggests involvement of RTKs such as PDGFR, c-Met, Axl, IGF1-R, EphB4 and ErbB4 as driver kinases in different sarcoma subtypes including synovial sarcoma, Ewing sarcoma as well as malignant peripheral nerve sheath tumor (MPNST)." (PMID 26675259, 2016). "It is an appealing strategy using BET inhibitors to block the IGF1 autocrine mechanism in Ewing sarcoma patients with high IGF1R expression, which is expected to spare normal tissues from toxicity of anti-IGF1R therapy." (PMID 27259270, 2016). "Responses to anti-IGF-1R therapy alone or in combination with mTOR inhibition in Ewing sarcoma patients have been reported, as have responses to Apo2L/TRAIL therapy in chondrosarcoma patients." (PMID 27486883, 2016). "It has been extensively documented that the IGF1R pathway is frequently activated in Ewing sarcoma and has important proliferative and prosurvival functions." (PMID 27259270, 2016). "The aim of the present study was to determine efficacy of cyclin-dependent kinase 4/6 (CDK4/6) and insulin-like growth factor-1 receptor (IGF-1R) inhibitors on the Ewing's sarcoma PDOX." (PMID 27286459, 2016). "More recently, IGF-1R has been shown to translocate to the nucleus in cancers for the prostate, renal, breast, soft tissue sarcomas, and Ewing sarcomas." (PMID 26217584, 2015). "Dysregulation of receptor tyrosine kinase signaling, particularly involving IGF-1R, also plays an important role in Ewing Sarcoma pathogenesis." (PMID 25603314, 2015). "We observed partial sensitization to OSI-906 upon PTEN re-expression in both cell lines, indicating that PTEN status contributes to sensitivity of Ewing Sarcoma cells to IGF-1R inhibition." (PMID 25603314, 2015).